RNU6-933P (RNA, U6 small nuclear 933, pseudogene)
Gene: Small nuclear RNA gene on chromosome 11 (60,985,061 to 60,985,167, reverse strand). Ensembl gene ENSG00000207153.
Homologues: Orthologues: chimpanzee U6 (97% identical), macaque U6 (80% identical), guinea pig U6 (74% identical). Paralogues in human: RNU6-12P (85% identical), RNU6-13P (85% identical), RNU6-32P (85% identical), RNU6-73P (85% identical), RNU6-1 (84% identical), RNU6-17P (84% identical), RNU6-18P (84% identical), RNU6-2 (84% identical), RNU6-20P (84% identical), RNU6-38P (84% identical), RNU6-3P (84% identical), RNU6-40P (84% identical), and 1288 more.